MRPL18 (mitochondrial ribosomal protein L18)
Description:
Together with thiosulfate sulfurtransferase (TST), acts as a mitochondrial import factor for the cytosolic 5S rRNA. The precursor form shows RNA chaperone activity; is able to fold the 5S rRNA into an import-competent conformation that is recognized by rhodanese (TST). Both the cytoplasmic and mitochondrial forms are able to bind to the helix IV-loop D in the gamma domain of the 5S rRNA.
Synonyms: L18mt; MRP-L18; HSPC071; uL18m
Tractability: Small molecule: a structure with a bound ligand is known. PROTAC: ubiquitination databases record sites on it; its protein half-life has been measured.
Gene: Protein-coding gene on chromosome 6 (159,789,812 to 159,799,027, forward strand). Ensembl gene ENSG00000112110.
Subcellular location: Mitochondrion
Subcellular location (Human Protein Atlas): Mitochondria
Pathways (Reactome):
Cellular responses to stimuli: Attenuation phase; HSF1 activation; HSF1-dependent transactivation; Regulation of HSF1-mediated heat shock response
Metabolism of proteins: Mitochondrial ribosome-associated quality control; Mitochondrial translation elongation; Mitochondrial translation initiation; Mitochondrial translation termination
Gene Ontology:
Molecular function: 5S rRNA binding; protein binding; structural constituent of ribosome
Biological process: rRNA import into mitochondrion; mitochondrial translation; translation
Cellular component: extracellular region; mitochondrial large ribosomal subunit; mitochondrion; mitochondrial inner membrane; mitochondrial ribosome; ribosome
Genetic constraint (gnomAD): Loss-of-function variants: 17 observed, 23.79 expected, observed/expected ratio (o/e) 0.71, 90% interval 0.49 to 1.07. The upper end of that interval is the gene's LOEUF score, 1.07, which puts it in group 4 of 6, group 1 being the genes least tolerant of losing a copy. Missense variants: 223 observed, 240.78 expected, observed/expected ratio (o/e) 0.93, 90% interval 0.83 to 1.03. Synonymous variants: 89 observed, 90.55 expected, observed/expected ratio (o/e) 0.98, 90% interval 0.83 to 1.17.
Homologues: Orthologues: chimpanzee MRPL18 (100% identical), macaque MRPL18 (97% identical), dog MRPL18 (91% identical), pig MRPL18 (88% identical), guinea pig MRPL18 (84% identical), mouse Mrpl18 (83% identical), rabbit MRPL18 (82% identical), rat Mrpl18 (77% identical), tropical clawed frog mrpl18 (57% identical), zebrafish mrpl18 (42% identical), Drosophila melanogaster mRpL18 (33% identical), Caenorhabditis elegans mrpl-18 (29% identical).
Diseases named in the same sentence as MRPL18 in open-access papers:
MRPL18 is named in the same sentence as 13 diseases in open-access papers, as found by Europe PMC text mining. Sharing a sentence is not in itself a finding about the gene and the disease. The quoted sentences say what the papers report.
breast carcinoma (2 papers, 2019 to 2025). "MRPL18 is highly expressed in breast cancer and is a risk factor." (PMID 40918472, 2025). "High levels of MRPL18 are considered a risk factor in breast cancer." (PMID 40918472, 2025). "In conclusion, our study provides strong evidence that MRPL18 is significantly overexpressed in breast cancer tissues." (PMID 40918472, 2025). "Taken together, these bioinformatic and experimental results demonstrate that MRPL18 promotes breast cancer cell proliferation and migration, supporting its function as a potential oncogene." (PMID 40918472, 2025). "Analysis indicated that MRPL18, along with N stage, M stage, and age, were significant factors in predicting overall survival in breast cancer (all p < 0.05)." (PMID 40918472, 2025). "Following CCK-8 and cloning experiments revealed that MRPL18 knockdown notably hindered cell proliferation, while its abnormal expression encouraged breast cancer cell growth." (PMID 40918472, 2025). "In vitro and in vivo studies demonstrated that MRPL18 promotes proliferation and migration in breast cancer." (PMID 40918472, 2025). "The study aimed to explore the clinical value of mitochondrial ribosomal protein L18 (MRPL18) in breast cancer." (PMID 40918472, 2025). "This study examined MRPL18’s role in breast cancer via numerous experiments and explored the expression level of MRPL18 and its clinical value using bioinformatics." (PMID 40918472, 2025). "This study comprehensively explored the role of MRPL18 in breast cancer by analyzing its expression data from multiple databases." (PMID 40918472, 2025). "Traswell and wound healing assays showed that MRPL18 promotes cell migration ability, while knockdown of MRPL18 was found to suppress the migratory ability of breast cancer cells." (PMID 40918472, 2025). "In a different study, high gene expression of a subset of MRPs including MRPL18 correlated with poor breast cancer survival, and predicted tumor recurrence and tamoxifen resistance." (PMID 31199051, 2019). "In addition, by examining data from 1087 patients in TCGA, MRPL18 expression was much less in healthy tissues when compared to breast cancer tissues (p < 0.001)." (PMID 40918472, 2025). "The results showed a notable rise in MRPL18 levels in breast cancer tissue." (PMID 40918472, 2025). "Ultimately, targeting MRPL18 may offer a viable strategy for improving clinical outcomes and advancing the field of breast cancer therapy." (PMID 40918472, 2025). "Additionally, transwell migration assays confirmed that MRPL18 enhances the migration ability of breast cancer cells." (PMID 40918472, 2025). "In subsequent studies, we might utilize organoids as a model to investigate the regulatory mechanisms of MRPL18 in the occurrence and progression of breast cancer, aiming to provide novel insights for personalized medicine." (PMID 40918472, 2025). "This study’s findings could aid in assessing MRPL18’s potential as a therapeutic target for breast cancer." (PMID 40918472, 2025). "Additionally, higher MRPL18 expression indicates a shorter OS in different subgroups of breast cancer." (PMID 40918472, 2025). "Consequently, future development of inhibitors aimed at the MRPL18 protein may increase the effectiveness of radiotherapy and chemotherapy in breast cancer treatment." (PMID 40918472, 2025).
Cachexia (1 paper, 2022). Severe weight loss, wasting of muscle, loss of appetite, and general debility related to a chronic disease. "Thus, musculoskeletal MRPL18 may be central in facilitating muscle oxidation, hinting a possible association between impaired muscle oxidative capacity, physical performance, and insulin resistance in ageing and cachexia-related NSCLC." (PMID 36067173, 2022).
Herpes simplex (1 paper, 2021). "Herpes simplex virus-1 (HSV-1) infection depletes the levels of RNA binding proteins (RBPs) (thiosulfate sulfurtransferase (TST), mitochondrial ribosomal protein L18 (MRPL18)) that typically shield pseudogene 5S rRNA (RNA5SP141)." (PMID 33444401, 2021).
Insulin resistance (1 paper, 2022). Increased resistance towards insulin, that is, diminished effectiveness of insulin in reducing blood glucose levels. "Additionally, abnormal MRPL18 responses have been involved with peroxisome proliferator-activated receptor γ coactivator-1β deficient mice in which dissociation between mitochondrial dysfunction and insulin resistance has been revealed." (PMID 36067173, 2022).
tumor (4 papers, 2017 to 2025). "Furthermore, MRPL18 expression was positively correlated with tumor mutation burden (p < 0.05)." (PMID 40918472, 2025). "Consistent with in vitro findings, it showed that overexpression of MRPL18 accelerated tumor growth and increased expression of Ki67 in tumor tissues." (PMID 40918472, 2025). "Single-sample GSEA was conducted to assess how MRPL18 expression influences immune infiltration within the tumor microenvironment." (PMID 40918472, 2025). "MRPL18 expression was improperly regulated, resulting in lower survival and tumor purity in non-small cell lung cancer, whereas in healthy older adults, the gene’s expression in tissues went the opposite way." (PMID 40918472, 2025). "Cell counting kit-8 (CCK-8) assays, colony formation, migration assays, flow cytometry, and xenograft models were employed to evaluate the role of MRPL18 in tumor progression." (PMID 40918472, 2025). "MRPL18 may promote an immunosuppressive tumor microenvironment, potentially reducing the efficacy of immunotherapy." (PMID 40918472, 2025). "Furthermore, functional enrichment analysis revealed that MRPL18 is involved in pathways critical to tumor survival and metastasis, including cell-substrate adhesion, adherens junction, cell adhesion mediator activity, PI3K-AKT pathway." (PMID 40918472, 2025). "Besides, results found that MRPL18 promotes tumor growth through the activation of phosphatidylinositol 3-kinase (PI3K)." (PMID 40918472, 2025). "The xenograft tumor model using nude mice to explore MRPL18’s impact on in vivo tumor growth." (PMID 40918472, 2025). "We identified four novel genes, KRTAP4-5, OR2T35, GPRIN1, and MRPL18, of unknown function in tumor progression and metastasis." (PMID 28249600, 2017). "Aligned with this observation, our analysis identified a strong positive correlation between MRPL18 expression and TMB levels, implying a possible influence of MRPL18 on the tumor’s immune context." (PMID 40918472, 2025). "Of them, > 40% were mitochondrial ribosomal proteins (MRPs) including MRPL18 and TIMM8B that we here report to be upregulated in diabetics both in the tumor and the mucosa." (PMID 31199051, 2019). "The results showed that subcutaneous tumors had notably reduced volume and weight in the si-MRPL18 group compared to the negative control group, while overexpression of MRPL18 tumor growth." (PMID 40918472, 2025). "Besides, MRPL18 was notably elevated in tumor tissue compared to matched normal breast tissue in 112 pairs of samples." (PMID 40918472, 2025).
cancer (1 paper, 2025). A tumor composed of atypical neoplastic, often pleomorphic cells that invade other tissues. "MRPL18’s involvement in the cytosolic stress response in mammalian cells, a key mechanism for cancer survival and progression." (PMID 40918472, 2025). "Nonetheless, the involvement of MRPL18 in cancer development and its molecular pathways are still not well understood." (PMID 40918472, 2025).
MRPL18 also shares sentences with these, for which no sentence is quoted: Alzheimer disease (1 paper); ataxia telangiectasia (1); depression (1); insulinoma (1); metabolic disorders (1); multiple sclerosis (1); psychosis (1).